LASP1 (LIM and SH3 protein 1)
Diseases named in the same sentence as LASP1 in open-access papers (continued):
Sharing a sentence is not in itself a finding about the gene and the disease.
invasive breast carcinoma (5 papers, 2007 to 2022). A carcinoma that infiltrates the breast parenchyma. "For example, in invasive breast cancer cells, LASP-1 expression was significantly inversely affected by prostate-derived ETS factor (PDEF), a transcription factor known to repress a variety of genes that are possibly involved in tumorigenesis." (PMID 22897902, 2012). "These experiments are supported by our present study proving the significantly higher expression of LASP-1 in invasive breast carcinomas compared to benign fibroadenomas." (PMID 17956604, 2007). "To test this hypothesis, we first confirmed that the gene expression of CXCR4, LASP1, and eIF4A are upregulated in invasive breast cancer." (PMID 31106142, 2019). "Like LASP-1, ENAH is not detectable in benign breast epithelium, but is weakly expressed in low-risk benign diseases like fibroadenomas and strongly expressed in invasive breast cancers." (PMID 17956604, 2007). "In contrast, staining intensity of LASP-1 in DCIS was not significantly higher than in fibroadenomas, but also not significantly lower than in invasive breast cancer." (PMID 17956604, 2007). "In invasive breast cancer cells, the potential tumor suppressor PDEF was identified to repress LASP-1 expression; however inverse correlation between LASP-1 and PDEF levels could not be demonstrated." (PMID 22897902, 2012).
chronic myeloid leukemia (4 papers, 2014 to 2020). "Recently, phosphorylation of LASP1 at Y171 by the oncogenic BCR-ABL tyrosine kinase in chronic myeloid leukemia (CML) patients was reported." (PMID 30298118, 2018). "In contrast to its expression in other leukemias, LASP1 is overexpressed and a direct substrate of the permanently active BCR-ABL oncogene in chronic myeloid leukemia (CML)." (PMID 25622104, 2015).
esophageal cancer (4 papers, 2017 to 2024). A primary or metastatic malignant neoplasm involving the esophagus. "miR-203 has been shown to regulate LASP1 in other squamous cell carcinomas, such as oesophageal cancer and HNSCC." (PMID 38789663, 2024).
glioma (4 papers, 2021 to 2023). A benign or malignant brain and spinal cord tumor that arises from glial cells (astrocytes, oligodendrocytes, ependymal cells). "In addition, miR-377-3p targeted LASP1 to decrease glioma cell proliferation and migration." (PMID 35057851, 2022). "For instance, circITGA7 accelerates glioma progression via miR-34a-5p/VEGFA axis; circSEPT9 promotes the malignant behaviors in glioma cells via miR-432-5p-mediated regulation of LASP1." (PMID 35059468, 2022).
melanoma (4 papers, 2015 to 2020). A malignant, usually aggressive tumor composed of atypical, neoplastic melanocytes. "This process is similar to the release of melanin vesicles in melanoma cells, a mechanism in part regulated by LASP1." (PMID 27588391, 2016). "Next, we used Western blot (WB) to analyze the expression of LASP1 in cultured normal human epidermal melanocytes (NHEMs) and different melanoma cell lines, which revealed LASP1 expression in NHEMs as well as in all studied melanoma cell lines." (PMID 26061439, 2015). "In the present study, we investigated the expression and function of LASP1 in normal skin, melanocytic nevi and malignant melanoma." (PMID 26061439, 2015). "A profound reduction of ~75% of LASP1 protein expression with maximum silencing after 72h is observed in the melanoma cells." (PMID 26061439, 2015). "Based on this definition 62.0% of the benign nevi, 13.8% of the primary melanoma and 4.7% of the melanoma metastases were scored LASP1-positive." (PMID 26061439, 2015). "We therefore assessed the LASP1 protein expression pattern by immunohistochemistry in specimens from 29 melanocytic nevi, 58 malignant melanoma samples and 20 melanoma metastases." (PMID 26061439, 2015). "To functionally assess the role of LASP1 in melanocytes and melanoma, we used NHEMs and two melanoma cell lines, i.e. UACC257 and MaMel2." (PMID 26061439, 2015). "To further examine a possible role of LASP1 in melanoma, we correlated LASP1 expression levels with clinicopathological parameters of the patients." (PMID 26061439, 2015). "We therefore analyzed i) the expression of potentially involved shuttle proteins in melanoma cells and ii) potential nuclear translocation of LASP1 after forskolin-triggered protein kinase A (PKA) activation." (PMID 26061439, 2015). "Correlation of LASP1 expression to clinicopathological parameters in melanoma." (PMID 26061439, 2015). "For further experiments, we chose MaMel2, a melanin-producing cell line derived from a subcutaneous melanoma metastasis that showed higher LASP1 levels than NHEMs, and UACC257, a slightly pigmented primary melanoma cell line with a LASP1 expression level similar to NHEMs." (PMID 26061439, 2015). "LASP1 expression in samples of melanocytic nevi, primary melanomas and melanoma metastases." (PMID 26061439, 2015). "Moreover, LASP1 is expressed in melanocytic nevi while in primary melanoma and in metastases LASP1 levels are reduced." (PMID 26061439, 2015). "As LASP1 is overexpressed in several cancer entities it was tempting to speculate that the protein might also be involved in the development and progression of melanoma." (PMID 26061439, 2015). "Interestingly in a melanoma study, LASP1 was described to be distinctly expressed only in the basal epidermal layer of the normal skin and in melanocytes while in primary melanoma and in metastases, a reduced LASP1 expression was noticed and no nuclear presence could be detected." (PMID 30298118, 2018). "75% of the LASP1-positive patients died (6 out of 8) compared to 38% of LASP1- negative patients (19 out of 50), assuming a trend to negative outcome for patients with LASP1 expression in melanoma." (PMID 26061439, 2015). "Melanoma is the first tumor tested so far, that is showing no LASP1 overexpression and obviously no involvement in the development and progression of melanoma." (PMID 26061439, 2015). "The observed low levels of LASP1 expression in melanoma and metastases are confirmed by microarray data set analysis, revealing no increase in LASP1 mRNA expression in melanoma when compared to normal skin." (PMID 26061439, 2015). "Melanoma exhibit no increase in LASP1 mRNA compared to normal skin." (PMID 26061439, 2015).
oral cancer (4 papers, 2013 to 2024). "It has been revealed that miR-342-3p acts as a tumor suppressor in oral cancer by inhibiting LIM and SH3 protein 1, and our results suggested that dysregulation of miR-342-3p also participated in the development of precancerous OSF." (PMID 39379100, 2024). "In oral cancer, miR-342 has been reported as being down-regulated, functioning as a tumour suppressor by targeting of LASP1." (PMID 37798371, 2023).
acute myeloid leukemia (3 papers, 2007 to 2014). Acute myeloid leukemia (AML) is a group of neoplasms arising from precursor cells committed to the myeloid cell-line differentiation. "Several additional observations underscore the important role of LASP-1 in cancer: Altered LASP-1 expression was associated with the MLL gene in acute myeloid leukemia through forming a new translocation-gene of the LASP1 and MLL gene in a patient with a high risk of stratification." (PMID 18419822, 2008). "First, altered expression of LASP-1 is associated with the MLL gene in acute myeloid leukaemia." (PMID 17211471, 2007).
Clear Cell Renal Cell Cancer (3 papers, 2014 to 2025). "LASP-1 overexpression has been described in several types of cancers, but its expression and role in clear cell renal cell cancer (ccRCC) remains unknown." (PMID 24955835, 2014). "In summary, our results suggest that NAT10 mediates ac4C acetylation of NFE2L3 mRNA, promotes its mRNA stability, regulates the LASP1-AKT/GSK3β/β-catenin axis and promotes the progression of renal clear cell carcinoma." (PMID 40169553, 2025).
endometrial cancer (3 papers, 2018 to 2024). Primary or metastatic malignant neoplasm involving the endometrium (mucous membrane that lines the endometrial cavity). "In line with this, literature data report that the NEB gene is frequently mutated in stage III endometrial cancer, and other genes of the Nebulin family, (e.g., LASP1, LASP2) are involved in cytoskeletal-architecture regulation and focal-adhesion organisation." (PMID 37626618, 2023).
glioblastoma (3 papers, 2018 to 2020). The most malignant astrocytic tumor (WHO grade IV). "Moreover, bioinformatics analysis showed LASP1 is upregulated in glioblastoma and related to poor overall survival, but the complex function and molecular mechanism of LASP1 in GBM remains largely unknown." (PMID 29980193, 2018). "However, the expression and intrinsic function of LASP1 in glioblastoma (GBM) remains unclear." (PMID 29980193, 2018).
leukemia (3 papers, 2014 to 2020). A malignant (clonal) hematologic disorder, involving hematopoietic stem cells and characterized by the presence of primitive or atypical myeloid or lymphoid cells in the bone marrow and the blood. "Known to be overexpressed in several cancer entities, we sought to investigate the LASP1 gene expression pattern in publicly available microarray datasets for leukemia and normal tissues." (PMID 24913448, 2014). "However, only the leukemia cell lines harboring Ph chromosome with constitutively active BCR-ABL (marked red) show a strong phosphorylation of LASP1 at tyrosine-171." (PMID 24913448, 2014).
lung adenocarcinoma (3 papers, 2016 to 2023). A carcinoma that arises from the lung and is characterized by the presence of malignant glandular epithelial cells. "In addition, we also analyzed the association between Lasp1 and clinicopathological features in lung adenocarcinomas or squamous cell lung carcinomas, separately." (PMID 29088849, 2017). "PF-562271, a specific inhibitor of FAK, was added into the medium after overexpressing Lasp1 in A549 (lung adenocarcinoma) and LK2 (squamous cell lung carcinoma) cells." (PMID 29088849, 2017). "Furthermore, we investigated whether pHLIP-miR-29a inhibits other target proteins including LASP1 and CDC42 associated with lung adenocarcinoma cell proliferation." (PMID 37684602, 2023). "In addition to CEACAM6, mir-29a also targets LASP1 and CDC42 and regulates proliferation, migration, and invasion of lung adenocarcinoma cells." (PMID 37684602, 2023).
metastatic cancers (3 papers, 2014 to 2018). A carcinoma which has spread from the original site of growth to another anatomic site. "Furthermore, LASP-1 silencing in metastatic cancer cell lines resulted in a strong inhibition of cell proliferation and migration, and led to zyxin reductions at the focal contacts." (PMID 24955835, 2014). "The LIM and SH3 protein 1 (LASP1), a structural scaffolding protein and adhesion adaptor protein, is involved in many metastatic cancers." (PMID 29531214, 2018).
pancreatic ductal adenocarcinoma (3 papers, 2015 to 2022). An infiltrating adenocarcinoma that arises from the epithelial cells of the pancreas. "In pancreatic ductal adenocarcinoma (PDAC) LASP1 has been identified as a target of the hypoxia regulated transcription factor HIF-1α." (PMID 25622104, 2015).
rheumatoid arthritis (3 papers, 2021 to 2025). A chronic, systemic autoimmune disorder characterized by inflammation in the synovial membranes and articular surfaces. "Patients with rheumatoid arthritis showed increased LASP1 levels while LASP1 deficiency altered the cell-to cell contacts and was associated with a less destructive phenotype." (PMID 36497077, 2022). "For example, METTL14 promotes the activation of fibroblast‐like synoviocytes (FLS) through the LASP1‐SRC‐AKT axis in rheumatoid arthritis." (PMID 41316520, 2025).
schizophrenia (3 papers, 2015 to 2023). A major psychotic disorder characterized by abnormalities in the perception or expression of reality. "Genetic variants and the expression level of LASP1 have also been associated with many neurological diseases, such as schizophrenia, autism, and bipolar disorder." (PMID 36895017, 2023). "Spatial working memory varied with LASP1 rs979607 polymorphisms of schizophrenia patients in this study." (PMID 31827227, 2019). "The aim of this study was to investigate the role of the LASP1 rs979607 polymorphism in the cognitive functions of patients with schizophrenia." (PMID 31827227, 2019). "A single-nucleotide polymorphism (rs979607) in the LASP1 gene promoter region has been also implicated in schizophrenia susceptibility." (PMID 31827227, 2019). "Case-control population study also showed that T allele of rs979607, a single nucleotide polymorphism (SNP) of the LASP1 gene promoter region, was associated with schizophrenia susceptibility in Korean population." (PMID 31827227, 2019). "Therefore, this study sought to test the influence of the LASP1 polymorphism (rs979607) on cognitive function of patients with schizophrenia." (PMID 31827227, 2019). "This association of LASP1 downregulation with schizophrenia in a mouse model is supported by a single nucleotide polymorphism (SNP) in the human LASP1 gene promoter region on chromosome 17, known to be associated with the susceptibility for schizophrenia in Korean population." (PMID 25622104, 2015). "Further studies with larger sample sizes of both schizophrenia patients and controls, various ethnicities, and longitudinal designs are needed to clarify the role of LASP1 in schizophrenia and cognitive functions." (PMID 31827227, 2019). "The LIM and SH3 domain protein (LASP1) protein, a component of CNS synapses and dendritic spines, has been related to the N-methyl-D-aspartate receptor (NMDAR) dysfunction hypothesis and schizophrenia." (PMID 31827227, 2019). "First: LASP1 is downregulated in mice treated with MK-801, the non-competitive antagonist of the NMDA receptor that constitutes an important animal model for schizophrenia studies." (PMID 25622104, 2015).
Arthritis (2 papers, 2021 to 2024). Inflammation of a joint. "Therefore, we show a function of Lasp1 in cellular junction formation and inflammatory tissue remodelling and identify Lasp1 as a potential target for treating inflammatory joint disorders associated with aggressive cellular transformation." (PMID 34131132, 2021). "Additionally, LASP1 may have pathogenic roles beyond cancer, with a recent study showing a role for LASP1 in regulating adherens junction dynamics in inflammatory diseases such as arthritis." (PMID 38789663, 2024).
autism (2 papers, 2008 to 2023). Persistent deficits in social interaction and communication and interaction as well as a markedly restricted repertoire of activity and interest as well as repetitive patterns of behavior. "Although the exact function of LASP-1 in CNS is still unclear a region on chromosome 17 has recently been highlighted in multiple studies as being linked to autism (MIM [209850])." (PMID 18419822, 2008). "Nominally significant single SNPs and/or haplotype-based association results were detected in 15 genes, of which, MYO1D, ACCN1 and LASP1 stand out as genes with autism risk alleles." (PMID 18419822, 2008).
cervical cancer (2 papers, 2022 to 2024). A primary or metastatic malignant neoplasm involving the cervix. "In this study, we demonstrate that LASP1 is upregulated in HPV positive (HPV + ) cervical cancer and it’s expression is significantly associated with worse overall survival." (PMID 38789663, 2024). "Here, our data demonstrate that LASP1 constitutes a novel oncogenic target of HPV E7 that may be an attractive therapeutic target for cervical cancer and other HPV-associated cancers." (PMID 38789663, 2024). "A complete characterisation of the LASP1 interactome is now warranted in order to determine if the functions of LASP1 can be targeted as a potential novel therapy in the treatment of HPV+ cervical cancers." (PMID 38789663, 2024). "Together, these data demonstrate that HPV induces LASP1 expression to promote proliferation and survival in cervical cancer, thus identifying a potential therapeutic target in these cancers." (PMID 38789663, 2024). "Depletion of LASP1, either transiently using siRNA or stably using shRNA, resulted in a significant proliferation defect in HPV+ cervical cancer cells, demonstrating the importance of LASP1 in driving the growth of these cancer cells." (PMID 38789663, 2024). "To assess if LASP1 was required for the invasive phenotype of HPV+ cervical cancer cells, we performed Transwell® assays." (PMID 38789663, 2024). "Our data demonstrated that the SH3 domain of LASP1 is critical for its ability to drive the proliferative and invasion phenotype in cervical cancer cells." (PMID 38789663, 2024). "We further show that the tumour suppressive functions of miR-203 in cervical cancer cells is dependent on its targeting of LASP1." (PMID 38789663, 2024). "Using a range of cervical cancer cell lines and patient tissue, we showed that LASP1 is highly expressed in HPV+ cervical cancer cells." (PMID 38789663, 2024). "We demonstrate that miR-203 targets LASP1 in HPV+ cervical cancer cells and that the tumour suppressive effects of miR-203 introduction are ablated when LASP1 expression is restored." (PMID 38789663, 2024). "Of particular note, we observed a reduction in HPV E6 and E7 expression upon LASP1 depletion in HPV+ cervical cancer cells." (PMID 38789663, 2024). "Together, these data demonstrate that LASP1 is a critical driver of HPV+ cervical cancer cell growth in vivo." (PMID 38789663, 2024). "LASP1 mRNA expression was upregulated in cervical cancer when compared with normal cervical tissue in several published datasets." (PMID 38789663, 2024). "In contrast, depletion of LASP1 had minimal impact on cell proliferation or colony formation in HPV- cervical cancer cells (C33A), as well as in HT-3 cells." (PMID 38789663, 2024). "Both HR-HPV E7 proteins resulted in increased LASP1 expression demonstrating that HR-HPV E7 promotes the expression of LASP1 in cervical cancer cells." (PMID 38789663, 2024). "Here, we demonstrate that the actin-binding protein LASP1 is upregulated in cervical cancer and significantly correlates with a poorer overall survival." (PMID 38789663, 2024). "To understand if miR-203 regulates LASP1 in cervical cancer, we first analysed a panel of cervical cytology samples and observed a significant inverse correlation between miR-203 levels and LASP1 mRNA expression." (PMID 38789663, 2024). "LASP1 protein expression was significantly higher in cervical cancer when compared to normal cervical tissue, consistent with our cell line data." (PMID 38789663, 2024). "We next analysed LASP1 expression in a panel of cervical cancer cell lines, using primary normal human keratinocytes (NHKs) as a control." (PMID 38789663, 2024). "To investigate the role of LASP1 in cervical cancer, we first depleted LASP1 using a pool of four specific siRNA." (PMID 38789663, 2024). "In HPV positive cervical cancer, LASP1 depletion significantly inhibited the oncogenic phenotype in vitro, whilst having minimal effects in HPV negative cervical cancer cells." (PMID 38789663, 2024).